PGR (progesterone receptor)
Diseases named in the same sentence as PGR in open-access papers (continued):
Sharing a sentence is not in itself a finding about the gene and the disease.
breast cancer (continued). "The current standard of care requires all newly diagnosed cases of invasive breast cancer to be routinely tested by immunohistochemistry (IHC) for the expression of estrogen receptor alpha (ER), progesterone receptor (PR) and the growth factor receptor HER2/neu (ERBB2)." (PMID 26717565, 2015). "Moreover, an ER−/PgR+ breast cancer cell line had been described earlier, indicating a mechanism of PgR expression regulation independent from ER-α." (PMID 26437901, 2015). "In breast cancer samples, ER and PgR expression status are evaluated by immunohistochemistry." (PMID 25774336, 2015). "The clinical and biological significance of ER-/PgR+ breast cancers has been debated." (PMID 26161666, 2015). "Of interest, in the Early Breast Cancer Trialists' Collaborative Group (EBCTCG) analysis, there was a non-significant association with reduced recurrences with adjuvant tamoxifen in the ER-/PgR+ phenotype despite this group being considered ER-negative." (PMID 26161666, 2015). "Consequently, the most common breast cancer phenotype expresses both ER and PgR, accounting for over 50% of all breast cancers." (PMID 26161666, 2015). "As a consequence, we analyzed our data to evidence the influence of cancer cell indicators such as the CDT and the expression of the most important diagnostic and prognostic immunohistochemical markers used for the characterization of breast cancer biopsy, namely ER, PgR and HER2." (PMID 26304457, 2015). "Among the four patients with deleterious mutations, 3 had family history of breast cancer and 1 had bilateral breast cancer, and 2 had triple-negative breast cancer (estrogen and progesterone receptor negative, and HER2/neu negative)." (PMID 26489409, 2015). "The ER−/PgR+ group accounts for 1 − 5 % of all breast cancers." (PMID 26437901, 2015). "Some efforts have been made to reveal the molecular essence of ER−/PgR+ breast cancer." (PMID 26437901, 2015). "Basal-like breast cancer is an aggressive subtype generally characterized as poor prognosis and lacking the expression of the three most important clinical biomarkers, estrogen receptor, progesterone receptor, and HER2." (PMID 26670335, 2015). "Overexpression of the progesterone receptor (PR) isoform A (PR-A) is a negative prognosticator for estrogen receptor (ER)-positive breast cancer but in vitro studies have implicated PR-B in progestin-induced invasiveness." (PMID 26356672, 2015). "Lack of expression of PGR, together with loss of estrogen receptors and of Her-2/neu, identifies ‘triple negative’ breast cancers, which are an aggressive, poor-outcome breast cancer subgroup." (PMID 25986046, 2015). "This clearly suggests that the three possible positive steroid receptor breast cancer phenotypes (ER+PgR+, ER+PgR− and the rare ER−PgR+) may be biologically different, particularly in this early phase of tumor growth, during tissue invasion." (PMID 24917206, 2014). "Activation of β-catenin is reported in subgroup of triple negative breast cancers (i.e., aggressive breast cancers possessing lack of estrogen receptor, progesterone receptor, and Her2 receptor expression) and is associated with poor clinical outcomes." (PMID 25491510, 2014). "Previous study has shown that AZD8931 inhibits human tumor xenograft growth with different sensitivities to agents targeting either EGFR or HER2 in a variety of models including one human breast cancer cell line BT-474, which expresses ER/PgR, high levels of HER2, and moderate levels of EGFR." (PMID 24886365, 2014). "Triple-negative breast cancer (TNBC) is recognized as a subtype of breast cancer in which three receptors [estrogen receptor (ER), progesterone receptor and human epidermal growth factor receptor 2] are negatively expressed on the surface of breast cancer cells." (PMID 24396484, 2014).
breast cancer (continued). "The expression of immunohistochemical markers of human epidermal growth factor receptor 2 (HER2/neu), estrogen receptor (ER) and progesterone receptor (PR) have been widely accepted for routine use in breast cancer, serving as predictive factors of endocrine and trastuzumab therapy, respectively." (PMID 24699941, 2014). "Despite the pleiotropic effects of the progesterone receptor in breast cancer, the molecular mechanisms in play remain largely unknown." (PMID 24897521, 2014). "As we know, triple-negative breast cancer (TNBC), which is characterized by negativity for estrogen receptor, progesterone receptor, and human epidermal growth factor receptor 2 (HER2) is a high risk breast cancer that lacks specific targets for treatment selection." (PMID 24883070, 2014). "Rictor expression significantly correlated with PgR expression (Pearson’s correlation coefficient r = 54) and was inversely related to Raptor expression (Pearson’s correlation coefficient r = −0.41) in breast cancers possessing a luminal B subtype." (PMID 25283550, 2014). "In fact, selective progesterone receptor modulators inducing Stat6 cofactor recruitment to PR could prevent breast cancer development when used in HRT, contraceptives, or treatment of uterine diseases." (PMID 24401087, 2014). "Additionally characterized on the breast cancer cells are three important receptors: estrogen receptor (ER), progesterone receptor (PR), and ERBB2 (Her2), and the presence of these receptors can influence prognosis and treatment." (PMID 24918944, 2014). "The objectives of our study were to create a database of breast cancer patients in Central Kerala between January 2010 and December 2012 and analyze the proportions of estrogen receptor and progesterone receptor positivity in premenopausal and postmenopausal women with breast cancer." (PMID 24761803, 2014). "In patients randomized to the control arm, we did not observe an association between PIK3CA mutations, or any of the other tested molecular aberrations, and breast cancer prognosis, when corrected for known prognostic factors, such as the PgR status and histologic tumor grade." (PMID 24467828, 2014). "Approximately 70–75% of breast cancers express ER and/or progesterone receptor." (PMID 25106495, 2014). "The relationship between physical activity (PA) throughout life and the risk of postmenopausal breast cancer overall and by estrogen receptor (ER) and progesterone receptor (PR) status, has been reported, but without consistent results." (PMID 24580799, 2014). "Through miR-155 overexpression in the ER+ MCF-7 breast cancer cell line we demonstrate alterations in the mTOR signaling cascade can result in the loss of PgR expression without prior growth factor stimulation." (PMID 25283550, 2014). "MMP 1 and MMP 2 were associated with breast cancer overall and were associated with oestrogen receptor positive/progesterone positive cancers and with oestrogen positive/progesterone receptor negative tumours." (PMID 24800085, 2014). "Furthermore, a large percentage of basal-like breast cancers lack expression of estrogen receptor (ER) and progesterone receptor (PR), as well as HER2 (‘triple negative’ immunophenotype)." (PMID 24004841, 2013). "Aromatase inhibitors (AIs), such as anastrozole, are extensively utilized in the treatment of estrogen receptor (ER)+/progesterone receptor (PgR)+ postmenopausal breast cancer patients, as AIs block paracrine production of growth stimulating hormones at the tumor-cell level." (PMID 23408108, 2013). "In the GEM dataset (n = 2,731), progesterone receptor mRNA expression was associated with prognosis in ER+ breast cancer (adjusted P <0.001), but not in ER- breast cancer (adjusted P = 0.21)." (PMID 23971947, 2013). "In recent years, breast cancer has been classified on the basis of estrogen or progesterone receptor (ER/PR) status and whether the human epidermal growth factor 2 receptor (HER2/neu) protein is overexpressed." (PMID 29147364, 2013).
breast cancer (continued). "Other factors that may affect the prognosis of breast cancer include the size of primary breast cancer tumor and tumor expression of the estrogen receptor, progesterone receptor, or HER2." (PMID 23626682, 2013). "We did not observe an association between PGR rs1042838 and breast cancer risk, in agreement with nearly all previous studies." (PMID 23935996, 2013). "Finally, a set of 16 different breast cancer cells, clustered by ERα, progesterone receptor (PR) and HER2 expression was also analyzed for the expression of miR-191, miR-425 and the host gene DALRD3." (PMID 23505378, 2013). "In breast cancer cases, the status of 17βHSD1 immunoreactivity in carcinoma cells was reported to be significantly correlated with that of ER and PgR, suggesting that E2, synthesized by 17βHSD1 in carcinoma cells may act on these cells locally." (PMID 23837683, 2013). "In the treatment of breast cancer patients classical clinicopathological parameters together with estrogen (ER) and progesterone receptor (PR) and human epidermal growth factor receptor-2 (HER2) status are currently applied to stratify patients into high and low risk groups." (PMID 24330623, 2013). "Elevated BMP7 levels are reported to be correlated with the depth of colorectal tumor invasion, liver metastasis and cancer-related death, as well as the levels of estrogen and progesterone receptor, both of which are important markers for breast cancer prognosis and therapy." (PMID 24161199, 2013). "We used polytomous logistic regression to calculate breast cancer odds according to tumor type, histopathological characteristics, and receptor (estrogen receptor (ER), progesterone receptor (PR), human epidermal growth factor receptor (HER2)) status by age (<55, 55–64, and ≥65 years)." (PMID 24188089, 2013). "CD163+ macrophages in tumor stroma positively correlated with higher grade, larger tumor size, Ki67 positivity, estrogen receptor negativity, progesterone receptor negativity, triple-negative/basal-like breast cancer and inversely correlated with luminal A breast cancer." (PMID 22824040, 2012). "Of the 363 breast cancers, 258 (71.1%) were ER positive and 218 (60.1%) were PgR positive." (PMID 22830453, 2012). "For all-cause and breast cancer-specific death, the trends were not significantly different between ER + or PgR + and ER-/PgR- women with BMI ≥21.2 kg/m2 (P for heterogeneity of trends = 0.10 and 0.13, respectively)." (PMID 22510365, 2012). "An inverse correlation between Skp2 expression and the expression of ER and PGR has been reported by others investigating breast cancer and other studies suggest that Skp2B may modulate the activity of the estrogen receptor." (PMID 23071715, 2012). "If there are very strong correlations between two or more variables in a model (for example, between age, estrogen and progesterone receptor in breast cancer), effects estimated from the model can be very unstable and difficult to interpret, requiring great care in model building (see Item 10d)." (PMID 22642691, 2012). "Moreover, modulation of estrogen and progesterone receptor signaling has been a long-standing approach to treating breast cancer and both estrogen and progesterone receptors are clients of HSP90." (PMID 24280702, 2012). "Promoter methylation of UCHL1 was detected in 9 of 10 breast cancer cell lines (90%) and 53 of 66 (80%) primary tumors, but rarely in normal breast tissues, which was statistically correlated with advanced clinical stage and progesterone receptor status." (PMID 22279545, 2012). "The risk of breast cancer related to CD44 rs13347 genotypes were further examined with stratification by age, age at menarche, menstrual history, BMI and family history of breast cancer, pathological type, clinical stage, estrogen receptor status and progesterone receptor status." (PMID 22788972, 2012).
breast cancer (continued). "Moreover, a positive progesterone receptor status is usually correlated with a positive oestrogen receptor status and favourable prognosis in human breast cancer." (PMID 23236990, 2012). "This shows that CTC together with a negative progesterone receptor status and N-stage are independent predictors for death due to breast cancer-related causes." (PMID 23088337, 2012). "An immunohistochemical analysis indicates that AR and GCDFP-15 are highly and specifically expressed in more than 80% and 90% of patients with SDC, respectively, whereas ER and PgR, well known as common breast carcinoma markers, are very weakly or negatively stained." (PMID 22647549, 2012). "There have been a number of studies investigating the ER/PgR status in contralateral breast cancer." (PMID 22091428, 2011). "Breast cancer represents a heterogeneous disease and the currently most relevant clinical classification is based on the expression of the estrogen receptor (ER), progesteron receptor (PgR), as well as the human epidermal growth factor receptor 2 (HER2)." (PMID 22220191, 2011). "When considering breast cancer irrespective of the ER or PgR expression status, CD138 expression is associated with the worst prognostic marker Her2/neu." (PMID 22214534, 2011). "Estrogen and progesterone receptor testing has become an essential part of the clinical evaluation of breast carcinoma patients, and accurate results are critical in identifying patients who may benefit from hormone therapy." (PMID 21971899, 2011). "Recently, a study reported an association between serum levels of estradiol and gene expression of trefoil factor 1 (TFF1), growth regulation by estrogen in breast cancer 1 (GREB1), PDZ domain containing 1 (PDZK1) and progesterone receptor (PGR) in ER+ breast carcinomas." (PMID 21812955, 2011). "In breast cancer PgR expression represents a clinically important indicator of prognosis." (PMID 20550710, 2010). "Therefore, both the ER and PgR expressions are still important markers for clinical decision-making in breast cancer." (PMID 29147190, 2010). "Interestingly, the choline concentration in triple negative breast cancer was higher than in ER+/PgR+ breast cancer." (PMID 20716336, 2010). "Breast cancer in AA women is characterized by earlier age at onset, later stage at diagnosis, higher nuclear grade, higher mitotic index and lower prevalence of estrogen receptor (ER) and/or progesterone receptor (PR) expression compared with EA women." (PMID 21060830, 2010). "The rs9397435[G] allele was found to confer significant risk of both ER positive and ER negative breast cancer and of both progesterone receptor positive and negative disease." (PMID 20661439, 2010). "Besides ER status, other documented genetic variables important in breast cancer research include progesterone receptor status (PR), the HER2/neu receptor, and the BRCA1 and BRCA2 mutation status." (PMID 20964848, 2010). "In breast cancer, Src activity and distribution might impact on resistance to endocrine therapy in patients with oestrogen receptor/progesterone receptor (ER/PgR)-positive disease." (PMID 20717116, 2010). "Therefore, the ER+/PgR+ phenotype is considered to be a valid surrogate marker for luminal-like subtypes of breast cancer." (PMID 20716336, 2010). "Results from recent clinical trials with aromatase inhibitors, agents that suppress estrogen synthesis through peripheral aromatization, in postmenopausal women with ER- or progesterone-receptor-positive breast cancer reinforce the importance of estrogen in breast-cancer growth." (PMID 20831839, 2010). "As the biology resulting in breast cancer pathological subtypes is different, we further hypothesized that specific aUPD regions might correlate with estrogen receptor (ER), progesterone receptor (PR), and/or HER2/neu status." (PMID 21152100, 2010).
breast cancer (continued). "Since previous studies have shown that progesterone receptor activates the Src/p21ras/ERK pathway via cross-talk with estrogen receptor in breast cancer, the positive correlation between HBO1 protein levels and PR which we obtained in statistical analysis was reasonable." (PMID 21040551, 2010). "We recently described the distribution and five-year survival of the subtypes of breast cancer based on estrogen receptor (ER), progesterone receptor (PR), and human epidermal growth factor receptor 2 (HER2), and found wide variation in survival especially among the HER2-positive group of patients." (PMID 20492696, 2010). "Coexpression of PgR and 4ICD is also commonly observed in ERα positive breast carcinomas." (PMID 20550710, 2010). "According to international treatment guidelines for early breast cancer, patients with ERα and/or progesterone receptor (PR) expression should receive an adjuvant endocrine therapy, since their expression is associated with higher response rates to anti-hormonal treatment." (PMID 19549328, 2009). "In contrast, the ER and PgR factors are only found in breast cancers." (PMID 19225561, 2009). "Steroid hormone receptors, ER and PgR, are important biological markers of breast carcinoma." (PMID 19591668, 2009). "Furthermore they observed an interesting correlation between the expression of miRNAs and specific breast cancer biopathologic features, such as tumour stage, proliferation index, oestrogen and progesterone receptor expression, and vascular invasion." (PMID 18631387, 2008). "We presently investigated the activity of bevacizumab in combination with chemotherapy, including capecitabine and vinorelbine, and endocrine therapy, including letrozole (+triptorelin in premenopausal women), as primary therapy for patients with ER and/or PgR ⩾10% T2–T4a-c, N0–N2, M0 breast cancer." (PMID 18941458, 2008). "As HER2-positive breast carcinomas are often associated with negative oestrogen and progesterone receptor status these findings are in concordance with the results from our immunohistochemistry data." (PMID 18254960, 2008). "Intriguingly, HER2-positive breast carcinomas are often associated with negative oestrogen and progesterone receptor status." (PMID 18254960, 2008). "Histologic cross sections of breast tumoroids developed in co-culture suspensions of breast cancer cell lines, stained for E-cadherin and progesterone receptor, were digitized and pixels in these images were classified into five categories using k-means clustering." (PMID 17822559, 2007). "Recently, Oh and coworkers have attempted to integrate data on estrogen responsiveness in MCF-7 cells in vitro with gene expression and clinical outcome data from 65 ER-positive and/or PgR-positive breast cancer patients to predict outcome for hormone responsive breast cancer." (PMID 17555561, 2007). "In the present study, we investigated the antitumour activity and expression of biological factors in a selected population of premenopausal patients with locally advanced breast cancer whose tumours expressed both ER and progesterone receptor (PgR) in at least 10% of tumour cells." (PMID 17712311, 2007). "We have studied the anatomy of co-cultures of poorly invasive and highly invasive breast cancer cell lines using digitized cross section images immunohistochemically stained for E-cadherin (Ecad) and progesterone receptor (PR) by automated image analysis methods." (PMID 17822559, 2007). "The circumscription of the tumour margin was significantly associated with negative PgR expression in a study conducted on 281 women with breast cancer in Finland." (PMID 17892570, 2007).